IL7 (interleukin 7)
Diseases named in the same sentence as IL7 in open-access papers (continued):
Sharing a sentence is not in itself a finding about the gene and the disease.
COVID-19 (continued). "A case report from Hospices Civils de Lyon, France, showed that a period of recombinant human IL-7 (rhIL-7) treatment remarkably improved the immune function in a 74-year-old ICU patient with severe COVID-19, which manifested as elevated lymphocyte count and mHLA-DR expression." (PMID 34234112, 2021). "Thus, further studies are warranted to understand the relation between IL-7Ra (CD127) expression and plasma/serum levels of IL-7 in COVID-19 patients." (PMID 34603318, 2021). "Analysis of plasma from patients with COVID-19 has revealed increases in cytokines, including IL-1β, IL-2, IL-6, IL-7, IL-10, TNFα, monocyte chemoattractant protein (MCP1/CCL2), granulocyte colony stimulating factor (G-CSF), and macrophage inflammatory protein 1α (MIP1α/CCL3)." (PMID 34251989, 2021). "NDG from severe/critical COVID-19 patients may be primed in vivo to spontaneously produce NETs, since they are exposed to IL-6, IL-2, IL-7, TNF, CXCL10, MCP-1, MIP1a, GM-CSF and M-CSF during the cytokine storm." (PMID 34685525, 2021). "Severely ill patients hospitalised with COVID-19 exhibit increased levels of many cytokines, including Interleukin (IL)-1β, IL-2, IL-6, IL-7, IL-8, IL-10, IL-17, granulocyte colony stimulating factor (G-CSF), monocyte chemoattractant protein 1 (MCP-1) and tumor necrosis factor (TNF)." (PMID 34205262, 2021). "It is worth noting that lower IL-7 in COVID-19 patients may compromise adaptive immunity since it plays an important role in the maintenance of mature T cells, and it also contributes to B cell development." (PMID 33947753, 2021). "Altogether, these studies confirm that plasma/serum IL-7 is elevated in COVID-19 patients and may be useful to measure the severity of the disease." (PMID 34603318, 2021). "We found that 24-h stimulation with IL-7 could successfully restore the frequency of perforin expressing MAIT cells of COVID-19 patients, which suggests that IL-7 treatment might be beneficial in arming MAIT cells affected by SARS-CoV-2 infection." (PMID 34238985, 2021). "Thus, the ongoing clinical trials and new studies should address the safety and efficacy of IL-7, its ability to reduce the viral load, and the survival rate of IL-7 treated COVID-19 patients." (PMID 34603318, 2021). "Moreover, serum IL-7 levels were significantly higher in severe COVID-19 patients compared to healthy controls and patient with mild symptoms." (PMID 34603318, 2021). "This study raises the premise that the cytokine storm observed in COVID-19 cases might be correlated with disease severity, as IL-2, IL-7, IL-10, G-CSF, MCP-1, IP-10, TNF-α, and MIP-1α levels were higher in ICU patients compared with non-ICU ones." (PMID 33379162, 2020). "Cytokine storm was observed in severe COVID-19 patients with high levels of various serum cytokines, such as IL-2, IL-7, IL-10, TNF-α, granulocyte-colony stimulating factor (G-CSF), interferon gamma-induced protein 10 (IP-10; CXCL10), and monocyte chemotactic protein-1 (MCP-1)." (PMID 33251234, 2020). "In addition, the use of IL-7 as a treatment for COVID-19 patients has been evaluated and will be discussed further." (PMID 33193331, 2020). "Interestingly, IL-7 can be found increased in the serum of patients having either mild/moderate or severe forms of COVID-19, which possibly represents the attempts of the immune system to reverse lymphopenia and T cell exhaustion." (PMID 32764275, 2020). "In COVID-19, this cytokine storm is characterised by the increase of interleukin (IL)-2, IL-7, granulocyte-colony stimulating factor, IFN-γ, inducible protein (IP)-10, monocyte chemoattractant protein (MCP)-1, macrophage inflammatory protein (MIP) 1-α, and tumour necrosis factor (TNF)-α." (PMID 33101440, 2020). "Thus, profound T cell depletion during COVID-19 may similarly affect the T cell compartment for long periods, with increased IL-7 and IL-15 concentrations altering γc receptor levels." (PMID 41310351, 2025).
COVID-19 (continued). "Considering our observations in the animal infection model, we questioned whether a differential in the expression level of GM-CSFR/IL-7R in neutrophils of COVID-19 patients or the plasma concentrations of GM-CSF and/or IL-7 may explain the reduction in the B cell population." (PMID 39012145, 2024). "First, we studied the profile of different soluble pro-inflammatory cytokines (GM-CSF, TNF-α, IFN-γ, IL-1β, IL-2, IL-6, IL-7, IL-10, IL-17A, IL-21) and chemokines mediating monocyte and neutrophil recruitment (IL8, CCL3), whose exacerbated production is associated with severe COVID-19." (PMID 36675231, 2023). "Recent advances in the pathophysiologic understanding of coronavirus disease 2019 (COVID-19) suggests that cytokine release syndrome (CRS) has an association with the severity of disease, which is characterized by increased tumor necrosis factor α (TNF-α), interleukin (IL)-6, IL-2, IL-7, and IL-10." (PMID 35223745, 2022). "Finally, the reduced plasma IL-7 concentration in COVID-19 patients may contribute to the observed lymphopenia in these patients." (PMID 35284964, 2022). "The fact that FCBD:std reduced IL-7 expression only to a minor extent in comparison to dexamethasone or FCBD suggests that using purified phytocannabinoids may have an advantage over cannabis-derived fractions for COVID-19-like inflammation." (PMID 33446817, 2021). "A significant difference was observed in the levels of IL-6 and IL-7 between severe and mild patients at 1–3 days and 4–6 days since onset (p < 0.05 or p < 0.01), which is in accordance with the published literature about IL-6 as a severity predictor of COVID-19." (PMID 34925252, 2021). "IL-7 is known to be vital for T-cell homeostasis and autoimmune inflammatory condition and was reported to be upregulated in patients with COVID-19 with neurological conditions, but its importance for neuroinflammation and glial activation needs to be confirmed still." (PMID 34899189, 2021). "Moreover, antidepressant use has been associated with a reduced risk of intubation or death in hospitalized patients with COVID-19 because the inhibition of ASM decreases pro-inflammatory mediators such as IL-2, IL-6, IL-7, IL-10, TNF-α, C-reactive protein (CRP), and D-dimer." (PMID 34579284, 2021). "Moreover, IL-7 concentrations were higher in severe patients compared to the other groups, suggesting use of IL-7 levels as a possible biomarker in measuring the severity of COVID-19 patients." (PMID 34603318, 2021). "Cytokine storm due to the overproduction of proinflammatory cytokines, including interleukin (IL)-6, IL-7, IL-8, etc. in critically ill patients with COVID-19 is a critical phase of the disease that may lead to acute respiratory failure or multiple organ dysfunction." (PMID 33364433, 2021). "Importantly, IL-7 administered ex vivo restored T cell IFN-ɣ production in COVID-19 patients." (PMID 32687484, 2020). "The analysis of cord blood samples at Early and Intermediate convalescent COVID-19 showed increased levels of CCL11, CCL3, CCL4, CCL2, IL-1β, IFN-γ, IL1-Ra, G-CSF, and IL-7 and a decrease of IL-10 and IL-2 as compared with HC." (PMID 40821818, 2025). "The aim of this work was to evaluate the associations of polymorphisms in the TNF-α, IL-6, IL-8, IL-10, CCL5 and CXCL6 genes with COVID-19 outcomes and with the serum levels of IFN-α, IFN-γ, TNF-α, IL-1Ra, IL-6, IL-7, IL-10, CCL2, CCL3, CXCL8, CXCL10 and GCSF." (PMID 40881695, 2025). "We and others demonstrated that several cytokines and chemokines including IL‐2, IL‐6, IL‐7, IL‐10, IL-15, IL-17, IP‐10, MCP‐1, TNF‐α, GCSF were related to disease severity and mortality in COVID-19." (PMID 40315230, 2025). "Notably, IL-2R, IL-6, IL-7, IL-8, and IL-10 showed lower correlations with the metabolites for the worst outcomes, indicating that these cytokines might have different regulatory mechanisms during severe COVID-19." (PMID 41002992, 2025).
COVID-19 (continued). "Multiple studies have confirmed a positive correlation between the severity of COVID-19 and the levels of C-reactive protein (CRP), IL-2, IL-6, IL-7, IL-8, and TNF-α cytokines." (PMID 40371107, 2025). "In our study, interleukins (IL-1 α, IL-7, IL-17, and IL-18) and chemokines (CCL11 and CXCL1) were found increased in COVID-19-only." (PMID 41516165, 2025). "Kynurenine was strongly correlated with IL-10, IL-8, IL-7, IL-6, IL-2R, IL-12, and IFN-α levels in patients with COVID-19." (PMID 41002992, 2025). "In our outpatient study during the COVID-19 pandemic, we have observed a significantly higher expression of the cytokines MIP-1β, IL-8, MCP1, GM-CSF, and IL-7 in the premenopausal women group compared to the postmenopausal women group." (PMID 40356822, 2025). "Compared with age-matched unexposed elderly individuals, convalescent COVID-19 patients presented with more IFN-γ and less IL-7, while IL-2, IL-6, IL-10, IL-12p70, IL-33 and CCL19/MIP-3 were unchanged." (PMID 38424104, 2024). "In particular, elevated levels of IL-6, IL-7, IL-10, IL-17, IL-23, TNFα, IFN-γ, IFNα or IL-1β have been found in severe COVID-19 cases and have already profoundly been analysed in recent Meta-Analysis." (PMID 38298642, 2024). "Many cytokines have been reported at elevated levels in COVID-19 cases, including IL1-β, IL-6, IL-7, IL-8, TGF-β and TNF-α." (PMID 38914619, 2024). "Other components, such as interleukins (IL-2, IL-6, IL-7, IL-10) and TNF-α are connected to severe COVID-19 symptoms, where cytokine storm (a sudden increase in cytokines) occurs instead of a healthy immune response (Fricke-Galindo and Falfán-Valencia 2021)." (PMID 38240884, 2024). "Analysis of cytokine profiles showed increased plasma levels of IP-10, HGF, VEGF-A, IL-7, IL-18, and MCP-1/CCL2 in COVID-19 patients." (PMID 38486975, 2024). "Another study has expanded results with elevated levels of plasma cytokines (IL-2, IL-7, IL-10, G-CSF, IP-10, MCP-1, MIP-1α, and TNF-α) in COVID-19 patients requiring Intensive Care Unit (ICU) admission compared to non-ICU patients." (PMID 38568894, 2024). "During COVID-19 progression, abnormal levels of IL-1β, TNF-α, IL-2, IL-7, IL-12, macrophage colony-stimulating factor (M-CSF), granulocyte colony-stimulating factor (G-CSF), and others can be detected in patient’s blood." (PMID 36702907, 2023). "COVID-19 even impacts the cytokine network by accelerating the production of the cytokines, such as PDGF-bb and IL-7." (PMID 37242334, 2023). "It was reported that COVID-19 patients exhibited high plasma levels of C-C motif chemokine ligand 2 (CCL2), CXCL10, IFN-γ, IL-1β, IL-7, IL-8, IL-10 and TNF-α." (PMID 37251383, 2023). "Consistent with our findings in TB patients, prior COVID-19 led to reduced levels of IFN-γ, IL-1β, IL-7 and TNF-α in ORD patients." (PMID 38179046, 2023). "COVID-19 patients with ARDS exhibited higher serum levels of all cytokines and chemokines measured (IFNy, TNFa, IL-4, IL-6, IL-7, IL-8, IL-10, IL-13, MIP-1b, and MCP-1) compared to patients with COVID-19 pneumonia without ARDS (data not shown)." (PMID 37293294, 2023). "Interestingly, recent improvements in the pathophysiologic understanding of COVID-19 revealed that the severity of COVID-19 is strongly associated with cytokine release syndrome (CRS), which is characterized by elevated tumor necrosis factor (TNF-α), interleukin (IL)-6, IL-2, IL-7, and IL-10." (PMID 36770606, 2023). "A clinical study of COVID-19 patients in Wuhan found that plasma levels of TNFα, IL2, IL7, IL10, IP10, MCP1, MIP1A, and GSCF in patients in the intensive unit (ICU) were higher than in non-ICU patients." (PMID 36033885, 2022). "In COVID-19 patients, excessive release of cytokine, including IL1-β, IL-2, IL-6, IL-7, IL-8, IP10, MCP1, MIP1A, and tumor necrosis factor-α (TNF-α), exacerbated COVID-19 manifestation." (PMID 36203683, 2022).
COVID-19 (continued). "MMP-7, TGF-β, CCL2, CCL-3, CXCL-10, G-CSF, IFN gamma, IL-10, IL-2, IL-4, IL-6, IL-7, TNF-α, IL-6, and IGF-1 were studied for their correlation to lung involvement in COVID-19 patients." (PMID 36286038, 2022). "The chest CT image of COVID-19 patients showed ground-glass opacity, and compared with healthy adults, the plasma concentrations of IL-1β, IL-7, IL-8, IL-9, IL-10, IFN-γ, TNF-α, and VEGF of COVID-19 patients were all upregulated." (PMID 35874688, 2022). "The studies indicate that the levels of IL-2, IL-6, IL-7, IL-10, and TNF-α are elevated in COVID-19; moreover, the increased IL-6 levels were found to be associated with disease progression and severe cases." (PMID 35656183, 2022). "In male participants, EGF, GM-CSF, IL-1ra, IL-1α, IL-1β, IL-2, IL-4, IL-7, IL-15, EOTAXIN, MDC, MIP-1α, MIP-1β, IFNα2, and sCD40L were significantly lower in COVID-19 patients compared to controls." (PMID 36554094, 2022). "Acute inflammation increases cytokine load, such as IL-2, IL-7, and TNF, which contribute to the cytokine storm seen in COVID-19." (PMID 35746659, 2022). "In conclusion, patients with severe COVID-19 showed a leukocyte profile with predominance for myeloid markers and lower-surface markers for lymphocytes including CD127, a receptor for IL-7." (PMID 35625671, 2022). "The MVA-secreted hIL-7-Fc initiated the signaling pathway of the IL-7 by inducing the expression of the pSTAT5 in CD3+ T lymphocytes in both ICU patients with septic shock and COVID-19." (PMID 36045686, 2022). "MMP-7, TGF-β, CCL2, CCL-3, CXCL-10, G-CSF, IFN gamma, IL-10, IL-2, IL-4, IL-6, IL-7, TNF-α, IL-6, and IGF-1 were studied for their correlation with mortality in all 40 COVID-19 patients." (PMID 36286038, 2022). "Patients with COVID-19 appear to have delayed IFN responses that results in upregulation of the cytokines IL-6, IL-7 and TNF-α." (PMID 35601440, 2022). "Plasma levels of IL-2, IL-7, TNF-α, and other pro-inflammatory cytokines were elevated in COVID-19 patients, and levels of various inflammatory cytokines were higher in (ICU) patients than in non-ICU patients." (PMID 36299906, 2022). "Severe COVID-19 patients admitted to intensive care unit showed higher level of pro-inflammatory cytokine including MCP1, MIP1α, IL2, IL7 and TNFα." (PMID 36369012, 2022). "Serum levels of EGF, G-CSF, GM-CSF, IL-1ra, IL-1α, IL-1β, IL-2, IL-4, IL-7, IL-8, EOTAXIN, fractalkine, GRO, P-10, MDC, MIP-1α, MIP-1β, IFNα2, and sCD40L were significantly lower in female COVID-19 patients compared to controls." (PMID 36554094, 2022). "The gene expression profile of activated lung macrophages in COVID-19 displays similarity with sHLH and MAS macrophages, and both sHLH/MAS and SARS-CoV-2 – induced cytokine storms include IL-2, IL-7, G-CSF, IP-10, MCP-1, MIP-1α and 1β, and TNF-α elevations." (PMID 35401519, 2022). "Initial studies in Wuhan, China showed elevated IL-1β, IL-7, IL-8, IL-9, IL-10, FGF, G-CSF, GM-CSF, IFN-γ, IP-10, MCP-1α and 1β, MIP-1, PDGF, TNF-α, and VEGF concentrations in COVID-19 compared to uninfected individuals." (PMID 35401519, 2022). "The results show that MMP-7, TGF-β, IL-10, IL-7, TNF-α, and IL-6 were significantly correlated with high lung involvement in COVID-19 patients." (PMID 36286038, 2022). "This bridging study aimed at assessing the capacity of a novel MVA-based IL-7 expressing virotherapy to restore adaptive immunity of immunosuppressed ICU patients with septic shock and COVID-19." (PMID 36045686, 2022). "MMP-7, TGF-β, IL-10, IL-7, TNF-α, and IL-6 were correlated with high lung involvement in COVID-19 patients." (PMID 36286038, 2022). "It has been reported that the levels of many inflammatory markers, such as interleukin (IL)-6, IL-7, monocyte chemoattractant protein (MCP)-1, and macrophage inflammatory protein (MIP)-1α, are elevated in COVID-19 patients." (PMID 34925252, 2021). "COVID-19-related CRS patients exhibited increased plasma levels of IL-2, IL-7, IL-10, G-SCF, MCP-1, MIP-1α, and TNF-α." (PMID 34884813, 2021).
COVID-19 (continued). "Studies have shown a strong correlation between the severity of COVID-19 and concentrations of different cytokines, such as IL2, IL7, IL10, GCSF, MCP1, and TNF-alpha." (PMID 33796097, 2021). "High plasma levels of pro-inflammatory cytokines (interleukin-2, interleukin-7, granulocyte colony-stimulating factor, IP10, MCP1, MIP1A and tumor necrosis factor-α) have been observed in critically ill COVID-19 patients admitted to intensive care units." (PMID 33752721, 2021). "Previous studies have reported abnormal levels of IL-2, IL-6, IL-7, IL-10, CRP, and tumor necrosis factor-α in COVID-19 patients." (PMID 34242179, 2021). "Studies have shown that the levels of various cytokines such as IL-2R, IL-6, IL-10, IL-2, IL-7, GCSF and TNF-α are significantly higher in patients with severe COVID-19 compared with patients who have a mild disease." (PMID 34490065, 2021). "In contrast, the highest contributors to dimension 1 were IL-21, IL-2, IL-1b, IL-17A, GM-CSF, IFN-γ, IL-7 and CCL3, and these cytokines were significantly decreased in acute COVID-19 patients in comparison to HC." (PMID 34572439, 2021). "To interrogate the potential role of T cell activation–related biomarkers in COVID-19 immunopathogenesis, we measured levels of IL-2, sCD25 (or sIL-2Rα), soluble CD40 ligand (sCD40LG), soluble FAS ligand (sFASLG), IL-7, and IL-3." (PMID 33232303, 2021). "High levels of proinflammatory cytokines (e.g., IL-12, IL-7, monocyte chemoattractant protein-1 [MCP-1], TNF-α, and granulocyte colony-stimulating factor) are essential in the pathogenesis of COVID-19." (PMID 34725309, 2021). "According to a recent report analyzing 138 hospitalized patients with COVID-19 high plasma concentrations of cytokines and chemokines including IL-2, IL-7, IL-10, G-CSF, IP-10, MCP-1, MIP-1A, and TNF-α were observed in the COVID-19 severe cases." (PMID 33154753, 2020). "Hence, the proposed immune combat strategies for COVID-19 involve suppressing of the cytokine storm by employing antagonists of some key pro-inflammatory cytokines, increasing the beneficial cytokines such as IL7, Type I IFN, along with treatment using anti-viral agents." (PMID 32733487, 2020). "Patients with severe or fatal COVID-19 showed significantly higher levels of inflammatory factors, such as CRP, interleukin-6 (IL-6), interleukin-2 (IL-2) and interleukin-7 (IL-7)." (PMID 32719804, 2020). "A previous study demonstrated the changes in the levels of inflammatory cytokines, such as IL-2, IL-7, IL-10, and tumor necrosis factor (TNF)-α, in the serum of COVID-19 patients." (PMID 32484453, 2020). "Some of these proinflammatory cytokines, including IL-2, IL-7, IL-10, G-CSF, IP-10, MCP-1, MIP-1a, and TNF-α, are highly elevated in the blood of severely ill COVID-19 patients." (PMID 33101440, 2020). "The elevated levels of cytokines IL-7, IL-10, IL-6, and IFN-α are indicative of severe inflammatory response and cytokine storm in COVID-19 patients." (PMID 32784499, 2020). "Significantly up-regulated levels of cytokines and chemokines including IL1-β, IL1RA, IL10, IL9, IL8, IL7, basic FGF2, GCSF, GMCSF, IFNγ, IP10, MCP1, MIP1α, MIP1β, PDGFB, TNFα, and VEGFA in blood, have been confirmed in COVID-19 patients." (PMID 33041797, 2020). "Hospitalized patients with severe COVID-19 show high levels of IL-2, IL-7, IL-10, G-CSF, TNF, CXCL10, MCP1, and MIP1α in serum, suggesting that severe COVID-19 is dictated as a cytokine release syndrome (CRS), which is a disorder induced by cytokine storms." (PMID 33014208, 2020). "The cytokine storms are characterized by significant induction of specific cytokines such as IL-6, IL-2, IL-7, GM-CSF, and IFN-γ in COVID-19 patients, which are different from other respiratory viruses with the increase in cytokines such as IL-2, IL-10, IL-4, or IL-5." (PMID 41002992, 2025).